CRP (C-reactive protein)
Diseases named in the same sentence as CRP in open-access papers (continued):
Sharing a sentence is not in itself a finding about the gene and the disease.
metabolic syndrome (continued). "Furthermore, NMR metabolomics has been used to determine metabotypes that responded to vitamin D supplementation by improving metabolic syndrome-related risk markers including CRP, insulin, and HOMA scores." (PMID 36899329, 2023). "Dyslipidemia, diabetes, and metabolic syndrome are linked to elevated CRP." (PMID 37175603, 2023). "A previous study in the NESDA cohort adopting a similar approach showed that the AES profile was specifically associated with an inflammatory index (integrating CRP and IL-6 levels), a metabolic syndrome index (integrating the five metabolic syndrome components) and their combination." (PMID 37301859, 2023). "In addition, a high-quality cohort study in 2020 can support our conclusion that CRP increase is positively related to PC risk, but it is only significant in patients with metabolic syndromes." (PMID 36816931, 2023). "The associated mechanisms between periodontal disease and metabolic syndrome components were increased pro-inflammatory mediators (including different cytokines, ROS, and elevated CRP) and constant penetration of periodontal pathogenic bacteria into the bloodstream." (PMID 37629193, 2023). "BMI-related dyslipidemia and elevated C-reactive protein increase the risk of PE." (PMID 36556383, 2022). "Cardiovascular risk factors, metabolic syndromes (such as high body mass index, and high serum triglycerides), inflammation (such as increase in C-reactive protein and fibrinogen), and lifestyle (such as smoking, sedentary behavior, and increasing age) are associated with chronic pain." (PMID 36187006, 2022). "As a result of the previous research, CRP as an inflammatory marker could be a potential mediator in the assumed association between child maltreatment and the development of comorbid metabolic syndrome to MDD." (PMID 35910956, 2022). "Elevated CRP was proven to be positively associated with the presence of the metabolic syndrome." (PMID 35740504, 2022). "CRP is a ubiquitarian biomarker of inflammation tightly linked to IL-6 and may be useful for risk stratification in patients with metabolic syndrome, as previously showed by our group." (PMID 36362423, 2022). "CRP also participates in endothelial dysfunction, the production of vasodilators, and vascular remodeling, and increased CRP level is closely associated with vascular system pathology and metabolic syndrome." (PMID 35620114, 2022). "S-TMAO (microbial-derived choline metabolite) levels were dose-dependent associated with CVD outcomes and other indicators such as serum cholesterol, glycaemic indices (HbA1c, fasting plasma glucose), inflammation biomarkers (IL-6, CRP), overall cardiovascular risk, and metabolic syndrome." (PMID 36558520, 2022). "We also aimed to investigate whether circulating CRP levels mediated the association between child maltreatment and comorbid metabolic syndrome in participants with current depressed mood." (PMID 35910956, 2022). "Thus, our aim is to analyze the association between somatic maturation and alterations in metabolic syndrome risk and C-reactive protein (CRP) among adolescents, focusing on the effect of changes in trunk adiposity and sports participation." (PMID 34508111, 2021). "Although elevated CRP levels have been shown to be associated with metabolic syndrome, and to be an independent risk factor for coronary artery disease, CRP was in those studies not analyzed independently of individual factors such as BMI, as was done in our study." (PMID 34123365, 2021). "Moreover, dyslipidemia in PsA patients is associated with increased markers of inflammation, such as C-reactive protein (CRP), and with a higher risk of subclinical atherosclerosis." (PMID 34527685, 2021). "Additionally, CRP levels were measured to link the leaky-gut-related biomarkers to the inflammatory status, as low-grade inflammation is often associated with metabolic syndrome." (PMID 34940635, 2021).
metabolic syndrome (continued). "In the present study, carbohydrate intake was associated with metabolic syndrome, and this association may differ according to individuals’ CRP levels and dairy food intake." (PMID 34578975, 2021). "Thus, sports participation was associated with reductions in the risk of metabolic syndrome, trunk fat, and CRP through direct and indirect pathways." (PMID 34508111, 2021). "Animal studies have shown that magnesium deficiency induces inflammatory response; randomized controlled trials further report that magnesium treatments significantly decrease concentrations of C-reactive protein (CRP) among patients with metabolic syndrome or high risk of inflammation." (PMID 33401667, 2021). "In our study, CRP levels were higher in individuals with unhealthy metabolic profiles than in those with healthy metabolic profiles, indicating that they are certainly at risk for developing metabolic syndrome." (PMID 34086828, 2021). "In addition, changes in trunk fat over time were directly associated with alterations in metabolic syndrome risk and CRP." (PMID 34508111, 2021). "Additionally, the level of CRP was measured to link the LGMs to an inflammatory status, as low-grade inflammation is often associated with metabolic syndrome." (PMID 34940635, 2021). "Furthermore, dyslipidemia within hs-CRP ranges of 2.4–3 mg/l was associated with 3.34 times (95% CI: [1.36–8.17], P = 0.008) greater chance of getting CVDs." (PMID 32489776, 2020). "Additionally, in subgroup analysis, it was indicated that the GG subgroup of the mentioned CRP gene polymorphism has significant association with metabolic syndrome." (PMID 32879918, 2020). "Moreover, elevated CRP levels of this magnitude in metabolic syndrome were associated with increased liver enzyme activity." (PMID 31209255, 2019). "High levels of inflammatory mediators including C-reactive protein in people with high red and processed meat consumption also might be another reason for the increased risk of metabolic syndrome." (PMID 29565803, 2018). "The association between chronic inflammation and metabolic syndrome was linked to central adiposity, which was accompanied by a decrease of adiponectin formed in adipose tissue and increased secretion of inflammatory markers such as CRP." (PMID 30454030, 2018). "Yet, only one additional study conducted in a sample of 204 Jordanian men that included data on cortisol and inflammation could demonstrate a plausible link between work stress, saliva cortisol, CRP, and risk of metabolic syndrome (MtS)." (PMID 29125555, 2017). "In addition to elevated Framingham relative risk scores and CRP levels, prominent dyslipidemia has been observed in schizophrenia." (PMID 28396623, 2017). "Studies have shown that moderate alcohol consumption may result in higher rates of HDL-cholesterol and low C-reactive protein that minimize the likelihood of aggravations, such as dyslipidemia and decreased cardiovascular risk." (PMID 28777805, 2017). "In addition, some new risk factors, including dyslipidemia, increased blood levels of C-reactive protein, carotid intima-media thickness, metabolic syndrome (MetS), older age, and gender have been identified." (PMID 27536865, 2016). "It remains unclear, however, whether this association simply reflects the inflammatory milieu or whether it suggests a causative role of CRP in the progression of dyslipidemia and related cardiovascular disturbances." (PMID 27633999, 2016). "Elevated homocysteine levels, high circulating fibrinogen levels, dyslipidemia, an increased body mass index, high C-reactive protein (CRP) levels and malnutrition might increase the risk of cardiovascular disease in dialysis patients." (PMID 26375560, 2015). "Moreover, anthropometric measurements in childhood were associated with the risk of metabolic syndrome, hyperglycaemia or type 2 diabetes, and elevated level of high-sensitivity CRP in adults, irrespectively of BMI gain from childhood to adulthood." (PMID 25880559, 2015).
metabolic syndrome (continued). "PCOS, as one of the diseases that is associated with metabolic syndrome, also may have changes in inflammation factors such as C3,CRP, interleukin-6, tumor necrosis factor-a, and lipid profiles." (PMID 25904961, 2015). "Association of an elevated CRP level with the number of metabolic syndrome components." (PMID 26193292, 2015). "Human studies associate high levels of CRP with metabolic syndrome and T2D." (PMID 24915044, 2014). "By adjusting by CRP, a proinflammatory biomarker, we controlled for the confounder effect of inflammation, and thus, the association between ferritin levels, as a marker of excessive body iron stores, and the metabolic syndrome was strengthened." (PMID 24884526, 2014). "In the present population-based investigation, we confirm earlier findings that FTO-mediated adiposity increases the risk of metabolic syndrome and of increased CRP, fasting insulin, and triglyceride levels; increased systolic and diastolic blood pressure; and decreased concentrations of HDL-C." (PMID 23824655, 2013). "The major limitation of CRP is its low specificity in differentiating bacterial infection from autoimmune diseases and some hematological malignancies; CRP levels also are elevated by stress and cardiovascular disorders, which can be associated with metabolic syndrome." (PMID 23690657, 2013). "A significant association between high CRP and prevalence of metabolic syndrome has been reported." (PMID 23826157, 2013). "Few studies have reported the association between CRP and development of metabolic syndrome." (PMID 23690772, 2013). "One proposal could be to observe the systemic effect of GlcN, for instance on ultrasensitive CRP, a marker of molecular inflammation associated with metabolic syndrome." (PMID 23531101, 2013). "UA is associated with Metabolic Syndrome and its components, obesity, dyslipidemia, hypertension, insulin resistance (metabolic syndrome), increased C-reactive protein (PCR) concentration and endothelial dysfunction, or even, to risk factors for cardiovascular diseases." (PMID 22475652, 2012). "First, markers of the inflammatory response such as tumor necrosis factor-alpha (TNF-alpha), interleukin-1β (IL-1β), interleukin 6 (IL-6), plasminogen activator inhibitor 1 (PAI1), and C-reactive protein (CRP) are strongly associated with features of the metabolic syndrome in humans." (PMID 22479352, 2012). "Elevated leptin and low CRP levels were associated with metabolic syndrome in both men and women." (PMID 22533665, 2012). "In the present study, leptin and CRP levels were associated with metabolic syndrome score, indicating that high levels of these markers may be predictive of developing metabolic syndrome similarly to that shown for high baseline fasting insulin levels." (PMID 22533665, 2012). "Our finding of adolescent emotional problems being associated with elevated risk for the metabolic syndrome only in rs1205 CC homozygotes may be linked to their higher CRP levels." (PMID 21296145, 2011). "► CRP gene helps identifying depressed people at high risk for metabolic syndrome." (PMID 21296145, 2011). "However, we showed an interaction between CRP rs1205 and affective status on the risk of the metabolic syndrome." (PMID 21296145, 2011). "In humans, high serum fetuin-A levels were found to be positively associated with metabolic syndrome and CRP, suggesting that fetuin-A may be causally involved in the pathophysiology of the condition of subclinical inflammation." (PMID 21556362, 2011). "In the current study, we hypothesize that the CRP gene is an important candidate gene for understanding the affective status–metabolic syndrome association." (PMID 21296145, 2011). "Importantly, the anti-PDI - metabolic syndrome association remained significant after adjusting for CRP and fasting insulin." (PMID 21949836, 2011).
metabolic syndrome (continued). "Therefore, the aim of this study was to compare associations of high sensitivity C-creative protein (hs-CRP) with metabolic syndrome and its components between men and women." (PMID 20663138, 2010). "Whether sex hormone is responsible for the association of metabolic syndrome with hs-CRP needs to be explored." (PMID 20663138, 2010). "There were two studies examining the association between CRP and metabolic syndrome in Chinese." (PMID 20663138, 2010). "Like stress, smoking is associated with dyslipidemia, atherosclerosis, and elevated CRP levels." (PMID 18426601, 2008). "Additionally, hs-CRP levels were linked to metabolic syndrome and low HDL-C levels." (PMID 40123888, 2025). "However, the causality between hs-CRP and dyslipidemia remains unresolved." (PMID 39859220, 2025). "Another study showed that higher depressive symptom scores reflected heavier metabolic syndrome severity in women and that both depressive symptom scores and metabolic syndrome severity scores were associated with lower physical activity levels and higher C-reactive protein levels." (PMID 37213540, 2023). "Notably, while CRP was also associated with increased risk in age‐ and sex‐adjusted models, this relationship not only disappeared, but in the case of metabolic syndrome in the younger ALSPAC cohort, was again reversed once other potential confounding factors such as BMI were considered." (PMID 35156387, 2022). "Based on the fact that prolonged dyslipidemia due to the chronic inflammatory process led to atherosclerotic plaque formation and an elevated risk of cardiovascular accidents, some studies suggested measuring of inflammatory markers such as CRP to assess cardiovascular risk." (PMID 35685585, 2022). "EAT thickness is associated with metabolic syndrome in a significant and independent way, according to several clinical studies, it is independently on other cardiometabolic risk factors, such as insulin resistance, fasting glucose, CRP, liver enzymes, and carotid intima-media thickness." (PMID 36743934, 2022). "Furthermore, because of their protective role against dyslipidemia, the three metals were also negatively correlated with plasma CRP levels, a classical cardiovascular risk factor that may play a direct role in atherogenesis." (PMID 36552647, 2022). "We also investigated whether socioeconomic status affected carbohydrate intake and whether the association of carbohydrate intake with metabolic syndrome differed according to participants’ CRP level and other food group intakes that were consumed as side dishes or snacks." (PMID 34578975, 2021). "In addition, increased serum concentrations of the acute-phase reactants C-reactive proteins (CRP) and high-sensitivity CRP (hs-CRP) are commonly used to monitor inflammation and are strongly associated with metabolic syndrome, atherosclerotic cardiovascular disease, and T2D." (PMID 33666873, 2021). "Consistent with the dysregulation in adipokine levels, metabolic syndrome has been associated an aggravation in inflammation, and this state that is characterized by increased pro-inflammatory cytokines and acute phase reactants such as CRP, IL-6, and tumor necrosis factor alpha (TNF-α)." (PMID 32375340, 2020). "Thus, it is recommended to incorporate more risk markers or indications, such as metabolic syndrome, plasma C-reactive protein (C-RP), coronary artery calcium (CAC), carotid intima media thickness (IMT) and the ankle brachial index (ABI) are incorporated to improve the prediction of CVEs." (PMID 31665091, 2019). "Therefore, through concurrently increasing serum CRP level, dyslipidemia plus OSA might enhance ASCVD risk in an OSA-severity dependant manner." (PMID 27228976, 2016).
metabolic syndrome (continued). "Dietary patterns poor in O3 may cause an excessive production of pro-inflammatory cytokines and CRP, while causing a lower production of anti-inflammatory cytokines, all recognized as contributing to the inflammation associated with metabolic syndrome and cardiovascular events." (PMID 23565815, 2013). "We also investigated whether two CRP gene polymorphisms (rs1205 and rs3093068) were associated with affective status and the metabolic syndrome, and whether the association between affective status and the metabolic syndrome was modified by these CRP polymorphisms." (PMID 21296145, 2011). "CRP is a well-recognised indicator of systemic inflammation, and chronic low-grade inflammation is considered a key contributor to the development of metabolic syndrome." (PMID 41524907, 2026). "Metabolic syndrome creates a systemic inflammatory environment characterized by elevated C-reactive protein, tumor necrosis factor-alpha, and interleukin-6 levels that can impair tissue repair processes." (PMID 41226877, 2025). "In contrast, the group with metabolic syndrome (G4) showed elevated levels of D-dimer, fibrinogen, and C-reactive protein." (PMID 40862415, 2025). "Reductions in CRP levels were observed in three studies, supporting the potential of curcumin to alleviate low-grade chronic inflammation typically seen in metabolic syndrome." (PMID 40868165, 2025). "Recently, the ABCD score, consisting of clinical presentation, myocardial bridge, C-reactive protein, and dyslipidemia, was developed to predict positive ACh test results." (PMID 40373526, 2025). "A key marker in this pathway is C-reactive protein (CRP), a liver-produced inflammatory biomarker triggered by interleukin-6 (IL-6) and other cytokines, and linked to elevated risk of CVD, metabolic syndrome, and related conditions." (PMID 40514590, 2025). "It has been argued that BMI and metabolic syndrome in particular can influence different inflammatory biomarkers, such as high-sensitivity CRP or the NLR." (PMID 40564216, 2025). "Numerous patients with metabolic syndrome exhibit elevated inflammatory marker concentrations, including C-reactive protein (CRP), tumor necrosis factor-alpha (TNF-α), and interleukin-6 (IL-6)." (PMID 41245414, 2025). "Obese subjects had higher CRP than normal (p < 0.001), dyslipidemia (p < 0.001), and HPT (p = 0.007)." (PMID 40299469, 2025). "In a large cohort study conducted by Park and Zhang, which analyzed the records of 40,768 patients, a correlation was found between metabolic syndrome, C-reactive protein levels, and white blood cell counts." (PMID 41523500, 2025). "This study also takes into consideration the role of serum vitamin D and C-reactive protein (CRP) levels, two important factors associated with NAFLD, in determining the classification of individuals within the different metabolic syndrome subclasses." (PMID 40093747, 2025). "A longitudinal study including 60 subjects with metabolic syndrome showed that, after six months of dietary treatment, DepS and the circulating CRP concentrations were decreased, and the decrease in DepS was significantly associated with declines in CRP." (PMID 40289959, 2025). "Their meta-analysis on patients with metabolic syndrome observed that berberine significantly reduced CRP by −1.54 mg/L, TNF-α by −1.02 pg/mL, and IL-6 by −1.17 pg/mL levels." (PMID 40006007, 2025). "They found significantly higher serum endocan levels (p < 0.001) and increased C-reactive protein levels (p < 0.001) in the metabolic syndrome group, indicating higher levels of endothelial dysfunction and systemic inflammation." (PMID 40722634, 2025). "Our study demonstrates a significant independent bidirectional association between dyslipidemia and CLD, which persists after adjustment for demographic confounders (sex, age, marital status) and metabolic covariates including IR and CRP levels." (PMID 40927334, 2025).